NRAS (NRAS proto-oncogene, GTPase)
Diseases named in the same sentence as NRAS in open-access papers (continued):
Sharing a sentence is not in itself a finding about the gene and the disease.
melanoma (continued). "Since BRAF and NRAS mutations were found to be mutually exclusive (further confirming previous data), a high prevalence of such alterations was observed in our series, with about two thirds of melanomas presenting a BRAF/NRAS mutation." (PMID 23987572, 2013). "According to the prevailing multistep model of melanoma development, oncogenic BRAF or NRAS mutations are crucial initial events in melanoma development." (PMID 23861977, 2013). "High numbers of BRAF and NRAS mutations were identified with frequencies varying according to melanoma subtype." (PMID 23694694, 2013). "At a molecular level it is believed that activation of the mitogen-activated protein kinase (MAPK) signaling pathway as a result of somatic mutations of NRAS or BRAF is a crucial event in this multistep development of melanoma." (PMID 23861977, 2013). "Considering the cases analyzed for mutations in both genes, we identified a BRAF or NRAS mutation in 339/528 (64%) melanoma lesions." (PMID 23987572, 2013). "In this study, we have characterized the BRAF and NRAS mutation status of a series of melanoma cell lines developed from New Zealand patients with metastatic melanoma." (PMID 23658559, 2013). "Activating mutations in the BRAF gene have been reported in 40–70% of melanomas and activating mutations in the NRAS gene in another 10–30%." (PMID 23658559, 2013). "The MAPK/Extracellular signal-regulated kinase (ERK) signaling pathway is commonly activated in melanoma by mutations in BRAF (in 50% of melanomas), NRAS (10–20%), and less frequently in MEK1 and MEK2 (∼8%)." (PMID 23515890, 2013). "Recently, NRAS/BRAF activation was shown to mediate an epithelial-to-mesenchymal transition (EMT) switch in late-stage melanoma that relies on TWIST1; ZEB1, and E-cadherin loss and results in enhanced invasion." (PMID 24416617, 2013). "Overall, BRAF or NRAS mutations were observed in 376/749 (50%) or 80/528 (15%) melanoma tissue samples, respectively." (PMID 23987572, 2013). "As expected, two NRAS-mutated melanomas showed little response even to relatively high doses of the drug." (PMID 22869096, 2012). "NRAS is the most commonly mutated Ras family member in melanoma, KRAS is predominantly mutated in colon cancer, while BRAF mutations are found in either malignancy." (PMID 22869096, 2012). "Several independent labs have demonstrated that melanoma can acquire resistance to vemurafenib in various ways, including mutation of NRAS, upregulation of CRAF or ARAF, redundant PI3-Kinase signaling or activation of COT." (PMID 23110092, 2012). "On the other hand, NRAS mutation failed in distinguishing melanomas on the basis of these morphological features." (PMID 22110486, 2012). "Mutations in BRAF occur in 40%-60% of melanomas and 15%-30% of melanomas harbour activating NRAS mutations." (PMID 22475322, 2012). "It has been shown to be effective when combined with dabrafenib in certain dabrafenib-resistant BRAF V600 melanoma lines that also had mutations at NRAS or MEK1." (PMID 23085539, 2012). "Oncogenic mutation in the sequence of the NRAS protein has been observed in around 15% of the melanomas leading to protein activation and transduction of survival and proliferation signals." (PMID 22216021, 2012). "As expected, BRAFV600 mutations were seen in 51% of the melanomas, whereas NRAS mutations were seen in 19% of the melanomas." (PMID 22912864, 2012). "PI3K pathway mutations co-occurred with BRAFV600 mutations in 17% of the tumors and co-occurred with 9% of NRAS mutant tumors, implying cooperativity between these pathways in terms of melanoma progression." (PMID 22912864, 2012). "The discovery that most human melanomas harbour mutations in either BRAF or NRAS has led to the development of targeted therapies, such as inhibitors of MEK or BRAF." (PMID 22475322, 2012). "Although the vast majority (>90%) of melanoma models harbored mutations in either BRAF or NRAS, significant differences in subcutaneous growth aggressiveness became obvious." (PMID 22535842, 2012).
melanoma (continued). "We confirmed the previously reported cytotoxic effect of a MEK inhibitor against cell lines with BRAFV600E mutations, but in addition the cytotoxic activity was evident in a high proportion of melanoma cell lines with NRAS, GNAQ or GNA11 driver mutations." (PMID 22515704, 2012). "The mutations in NRAS (typically associated with melanomas, multiple myelomas, acute myelogenous leukemia, and thyroid cancer) were, in both cases, the Q61R hotspot mutation in the Ras domain." (PMID 23383675, 2012). "Further testing with expanded panels of cell lines has confirmed a trend towards higher sensitivity in BRAFV600E mutant melanoma, but has also provided evidence that some melanoma cell lines with NRAS activating mutations are sensitive to MEK inhibitors." (PMID 22515704, 2012). "In tumor types with more than 10 patients tested, NRAS mutations were most frequent in melanoma, in 12 (30%) of 40 tested patients." (PMID 21829508, 2011). "An NRAS Q61K mutation was also identified in an isolated nodal metastasis from a patient with BRAF mutant melanoma, which progressed after an initial response to PLX4032." (PMID 21505228, 2011). "These were characterized by karyology, growth kinetics, and genotyping for the BRAF and NRAS mutations common in melanomas and nevi." (PMID 21418545, 2011). "We also found that the combination was effective in melanoma cells carrying either BRAF or NRAS activating mutations, since A375, 1205Lu, and WM239a lines each have BRAFV600 mutations, while WM852c and SBCL2 lines have NRASQ61 mutations." (PMID 21897876, 2011). "For example, NRAS is mutated in about 15% of melanoma and can activate both the signalling pathways." (PMID 21139585, 2011). "c-KIT aberrations do not seem to typically overlap with mutations such as B-RAF and NRAS even though these are amongst the most common mutations in melanoma." (PMID 21479172, 2011). "In melanoma, NRAS mutations have been identified in 10–25% of tumor samples and are thought to be an important driver of oncogenesis in these patients." (PMID 22175026, 2011). "Subtype 4.1 is characterized by mutations in NRAS, which are observed in approximately 20% of melanomas." (PMID 21479172, 2011). "In conclusion, our data suggest that single agent MEK inhibitor has low activity in vemurafenib-resistant melanoma and perhaps restricted to a subset of cases with secondary oncogenic mutations in NRAS." (PMID 22194965, 2011). "Although BRAF and NRAS mutations are mutually exclusive in the majority of melanomas, dual pathway signalling is also frequently seen in melanoma through functional loss (deletion, silencing and/or mutation) of the tumour suppressor gene PTEN." (PMID 21139585, 2011). "This is opposed to melanomas with NRAS mutations, since RAS mutations can provide oncogenic signal through both the MAPK and the PI3K/AKT pathways." (PMID 22194965, 2011). "In melanoma, only NRAS mutation and male gender were associated with shorter OS from time of diagnosis (HR: 2.16, 95% CI 1.11–4.18, p = 0.02 and HR: 2.64, 95% CI 1.28–5.41, p = 0.008, respectively)." (PMID 22039425, 2011). "Another important oncogene in melanoma is NRAS, and mutations in NRAS or BRAF are detected in almost all human melanoma." (PMID 20230482, 2010). "Initially, we assessed changes in MITF expression in six human melanoma lines harboring oncogenic mutations in BRAF or NRAS, and in which ATF2 expression was effectively inhibited by corresponding shRNA (shATF2)." (PMID 21203491, 2010). "NRAS mutations occur in approximately 15% of melanomas and are mutually exclusive with BRAF mutations." (PMID 20406486, 2010). "Melanoma cell lines harboring wild type NRAS and BRAF (37-31E and MeWo), NRASQ61L mutation (SKMel 103 and SKMel 147) or BRAFV600E mutation (UACC903, Colo 829) were grown in complete medium and in the presence of increasing concentrations of MTA." (PMID 20529342, 2010).
melanoma (continued). "BRAF and NRAS mutations have also been found in benign nevi and are therefore thought to be involved early in melanoma carcinogenesis." (PMID 20140953, 2010). "We report an investigation of gene dosage at 9p21.3 and mutations in BRAF and NRAS, as predictors of relapse and histological markers of poor melanoma prognosis." (PMID 20140953, 2010). "Somatic mutation frequencies of BRAF and NRAS, two signature oncogenes in melanoma, exhibit differential preferences for primary tumors arising from different anatomic sites associated with varying UV exposure histories." (PMID 20520718, 2010). "We have examined the role of BRAF and NRAS mutations and reduced gene dosage at 9p in melanoma relapse." (PMID 20140953, 2010). "Through an initial series of experiments, we confirmed that PLX4720 had good selectivity for BRAF-mutated melanoma cell lines over those harbouring NRAS mutations and also demonstrated that PLX4720 was able to induce significant levels of apoptosis." (PMID 20531415, 2010). "Erk1/2 kinase is downstream of BRAF and NRAS pathways, which are frequently mutated in human melanomas." (PMID 20701798, 2010). "Melanoma cell lines with different NRAS/BRAF mutational status were treated in vitro with a range of concentrations of PLX4032 for 5 days." (PMID 20406486, 2010). "10-20% of melanoma have point mutations in codon 12, 13 or 61 of NRAS, which are almost always mutually exclusive with BRAF mutation." (PMID 19949544, 2009). "Paired primary melanomas and lymph node metastases from same patients (N = 35) as well as melanoma cell lines (N = 18) were analyzed for somatic mutations in NRAS, BRAF, and p16CDKN2A genes." (PMID 19799798, 2009). "In NRAS mutated melanoma cells, CRAF was demonstrated to be the major RAS effector for signaling through ERK." (PMID 19492075, 2009). "NRAS mutations are also common in melanoma occurring in up to 30% of cases, and as the occurrence of NRAS or BRAF mutation in melanoma is mutually exclusive, up to 90% of melanomas harbour a mutated, hyperactive Ras–RAF signalling pathway." (PMID 19724275, 2009). "Regarding genetic events involved in melanoma pathogenesis at somatic level, mutually-exclusive mutations of NRAS and BRAF genes were observed at quite same rate (about two thirds) in cultured and in vivo melanomas (either primary or metastatic lesions)." (PMID 19799798, 2009). "NRAS mutations are rarely found in benign acquired nevi (although seen in congenital nevi), arise later in melanoma development, and can produce melanoma in certain animal models and are thus are more clearly implicated in oncogenesis than BRAF mutations." (PMID 19949544, 2009). "NRAS mutations are particularly frequent in melanoma, accounting for 15–25% of all melanomas." (PMID 40423070, 2025). "However, in melanoma cells presenting the NRAS mutation, vemurafenib is thought to inhibit only one RAF promoter in the dimer, whereas the other one remains active and maintains signals for downstream activation of MAPK/ERK pathway." (PMID 40141318, 2025). "The exact mechanism of how neutrophils are seen in NRAS-mutated melanoma BMs remains to be exposed." (PMID 40076927, 2025). "NRAS mutations in melanoma occur mainly at codon 61, with Q61R considered the most common." (PMID 41178942, 2025). "Therefore, we underline the association of BRAF- and NRAS-mutated melanomas with clinicopathologic features underlying a more aggressive melanoma phenotype." (PMID 40867317, 2025). "Targeted therapies against BRAF and NRAS mutations have been recently explored in melanomas." (PMID 41394861, 2025). "BRAF mutation was more frequently observed in ulcerated melanomas with a high mitotic rate ≥ 5 n/mm2 (a measure of how fast melanoma cells are growing), while NRAS mutation was associated with amelanotic/hypomelanotic (subtype with little or no pigmentation) and nodular melanoma." (PMID 40867317, 2025).
melanoma (continued). "In contrast, high-CSD melanomas frequently lack BRAF V600E mutations but may have alterations in genes such as NRAS, NF1, and KIT while exhibiting a higher TMB." (PMID 40125165, 2025). "This included the melanoma driver mutations NRAS Q61K/R, BRAF V600E, CDKN2A P114L, and HRAS G13." (PMID 40075679, 2025). "To demonstrate the hypothesis, we further characterized glutamine metabolism in melanoma cell lines (with mutations on BRAF, NRAS, or cKIT) that are resistant to RTKi/MAPKi and in tumor samples from melanoma patients." (PMID 40943167, 2025). "BRAF and NRAS mutations are common pathogenic mutations in melanoma." (PMID 40933889, 2025). "Several drugs have been developed to treat NRAS mutations in melanomas." (PMID 40423070, 2025). "Similarly, NRAS-mutant melanomas are also often associated with an inflammatory phenotype and are typically considered “hot” tumors." (PMID 41465101, 2025). "However, the impact of this paradoxical activation on mitochondrial dynamics and function in NRAS-mutated melanoma is unclear." (PMID 40141318, 2025). "Oncogenic mutations in NRas are frequently found in melanoma cells." (PMID 41373795, 2025). "Within advanced unresected melanoma, NRAS or BRAF mutation has little effect on ICI response." (PMID 40362630, 2025). "Despite vemurafenib’s low cytotoxicity in NRAS-mutated melanoma, targeting mitochondrial dynamics and/or oxidative phosphorylation may offer a promising strategy for combined therapy." (PMID 40141318, 2025). "NRAS mutations in melanoma patients are observed at rates of approximately 13-25%." (PMID 41142596, 2025). "Specifically, mucosal melanomas originating from upper sites and those harbouring NRAS mutations may more benefit from the combination therapy." (PMID 39757723, 2025). "Furthermore, mutations in two genes of the mitogen-activated protein kinase, BRAF and NRAS, have been implicated in 80% of melanoma cases." (PMID 41280706, 2025). "A recent study has shown a similar pattern in NRAS-mutated melanoma resistant to MEK inhibitor." (PMID 40667288, 2025). "Furthermore, mucosal melanoma of upper site and NRAS mutation appear to be good predictors of response to immune checkpoint inhibitor and anti‐angiogenic combination treatment." (PMID 39757723, 2025). "Additionally, mutations in the NF1 gene, often observed in melanomas arising on chronically sun-exposed skin, lead to hyperactivation of the NRAS–MAPK pathway and increased resistance to apoptosis." (PMID 40507265, 2025). "Loss of CDKN2A (encoding p16^INK4A) has been shown to cooperate with NRAS mutations to induce melanoma and may play a role in malignant progression." (PMID 41294657, 2025). "Moreover, NRAS mutations have been identified in both human and canine melanomas, contributing to tumor development in both species." (PMID 41394861, 2025). "NRAS mutations are typically found in melanomas, the colon, the thyroid, and bone marrow." (PMID 40423070, 2025). "Overall, the results of this study highlight the benefit of brimarafenib and mirdametinib combination treatment in NRAS mutated melanoma models and provide supportive preclinical evidence for the investigation of this combination approach in melanoma patients harboring NRAS or other RAS‐mutations." (PMID 41199020, 2025). "Consequently, preclinical studies that evaluate treatment strategies against other melanoma subtypes – such as those with mutant NRAS, NF1 loss, or triple wild-type have yet to be tested in this context." (PMID 40944916, 2025).
melanoma (continued). "Hence, we studied the mutual organization of wt NRas with the most frequent oncogenic mutation Q61R, found in 85% of melanoma cases incorporating NRas mutations." (PMID 41373795, 2025). "Then, we compared the cell growth-inhibiting effects of NRAS ASO-1 + 2 treatment to treatment with an NRAS-targeting ASO that is specifically directed to the mRNA sequence harboring the NRASQ61L mutational site (NRAS ASO-Q61L) in the NRASQ61L mutated melanoma cell lines D04 and MM415." (PMID 40473796, 2025). "However, NRAS-mutated melanomas still lack a specific inhibitor or chemotherapeutic drug for their treatment, remaining neglected." (PMID 40141318, 2025). "While trametinib, an FDA-approved targeted MEKi therapeutic for melanoma has improved the OS of patients with melanoma, most tumors with NRAS mutations are, at best, only partially responsive to MEKi-based therapy alone, and the development of resistance remains a challenge." (PMID 39996721, 2025). "The high frequency of BRAF and NRAS mutations in particular provides important insights into the molecular heterogeneity of melanomas and potential sensitivity to targeted therapies, while NF1 and PTEN mutations further illustrate the diversity of driver alterations in this population." (PMID 41142596, 2025). "If confirmed, targeting ACKR2 could represent a beneficial therapeutic approach in BRAF/NRAS-mutated melanoma patients." (PMID 40248897, 2025). "However, the synergistic effect of PDPK1 depletion and MEKi was further investigated in melanoma cell lines with NRAS-mutation." (PMID 41369373, 2025). "Of the cases with BRAF WT melanoma, nearly 15 to 30 percent have an NRAS mutation." (PMID 39940799, 2025). "In addition, since avutometinib binds MEK and locks the protein in a complex with RAF, this strategy should also be effective in melanomas driven by mutant NRAS or loss of neurofibromin (NF1)." (PMID 39922199, 2025). "However, our recent knowledge on the genetics of cutaneous melanoma is far more complex and identified actionable gene defects such as NRAS, KIT or IDH1 mutations and NRAS mutant melanoma are now in clinical trials." (PMID 40361349, 2025). "BRAF mutations occur in 60% of melanomas and NRAS mutations occur in 15%–20% of melanomas." (PMID 38586368, 2024). "The ribociclib and binimetinib combination has demonstrated effectiveness in NRAS‐mutated melanoma, especially in patients with additional cell cycle gene mutations (CDKN2A, CDK4, and CCND1), who may derive greater benefit from this therapy." (PMID 39564955, 2024). "NRAS is the second most frequently mutated oncogene in melanoma in up to 25% of cases." (PMID 39335684, 2024). "Additionally, mutations in the NRAS gene, such as NRAS Q61R, are found in about 15–20% of melanoma cases." (PMID 39061208, 2024). "NRAS-mutated melanomas are aggressive with a high risk of distant metastasis." (PMID 38247727, 2024). "In addition, NRAS mutations are prevalent in approximately 25% of melanoma and display an even more aggressive tumour progression than their BRAF-mutated counterparts, although the role of NRAS mutations only serve as a prognostic factor." (PMID 38127894, 2024). "Loss of NF1 function co-occurres also with the mutated BRAF and NRAS melanomas." (PMID 39340537, 2024). "In addition to the BRAF V600E/K mutant lines, Belvarafenib also inhibited most melanoma lines with a NRAS hotspot mutation (specifically Q61R, Q61K, Q61V, and Q61L) or the wild type for RAS/RAF proteins." (PMID 39199684, 2024). "For instance, canine melanoma with specific genetic mutations, such as NRAS and KIT, may be particularly amenable to treatment with small molecule inhibitors that target these mutations." (PMID 39408717, 2024).